EGFR (epidermal growth factor receptor)
Diseases named in the same sentence as EGFR in open-access papers (continued):
Sharing a sentence is not in itself a finding about the gene and the disease.
melanoma (continued). "Taken together, these data indicate that the uPAR interactome transferred by melanoma exos in target endothelial cells could play a prominent role in melanoma-associated tumor angiogenesis by control of EGFR signaling." (PMID 33237352, 2021). "Furthermore, among the NCI-60 cell lines investigated in this study, the leukemia RPMI-8226 and melanoma SK-MEL-28 cell lines were identified to harbor EGFR mutations which led to their resistance to 12 TKIs, including erlotinib." (PMID 34512327, 2021). "Furthermore, skin melanoma is characterized by frequent amplifications of BRAF (7q34), NRAS (1p13.2), KIT (4q11) oncogenes (major mutated genes in melanoma) but also by EGFR (7p11.2) and MET (7q31.2) genes." (PMID 34885093, 2021). "The authors also showed exosomal DNA could carry BRAF mutations, common mutations in malignant melanoma, and mutations in epidermal growth factor receptor (EGFR) in NSCLC." (PMID 33805398, 2021). "In human melanomas the overexpression of EGFR, HER3 or HER4 is associated with poor prognosis." (PMID 31996230, 2020). "BRAF/MEK inhibitor resistance in melanoma is associated with increased expression of EGFR." (PMID 32626712, 2020). "In melanoma, the presence of this mutation is indicative of response to anti-EGFR therapy." (PMID 30030291, 2018). "Despite their up-regulated expressions in VemR melanoma cells and definite associations with BRAFi resistance, EGFR, IGF-1R and CRAF might play different roles in development of resistance to BRAFi." (PMID 27448964, 2016). "Finally, epidermal-growth-factor receptor (EGFR) copy number alterations have been found in primary cutaneous malignant melanomas and their presence has been associated with poor prognosis." (PMID 26305188, 2015). "Cossetti C and their colleagues generated a mouse model xenografted with human melanoma cells stably expressing EGFR-encoding plasmid and found that EGFR RNA was released from the xenografted human cells into the bloodstream and eventually in spermatozoa of mice." (PMID 26452221, 2015). "We obtained the risk scores of patients with melanoma: risk score = (−0.379123977 × expression of IFNG) + (−0.662084468 × expression of DAPK2) + (0.342818269 × expression of ATG9B) + (0.406559238 × expression of PTK6) + (0.807218069 × expression of BIRC5) + (0.364523721 × expression of EGFR)." (PMID 36690663, 2023). "In addition to its pro-invasive role, stromal-derived HGF has been reported to promote the adhesion of CRC cells to endothelial cells, facilitating metastasis as well as to underlie the resistance mechanisms to RAF inhibitors in a melanoma model and to EGFR targeting in different cancer types." (PMID 36010567, 2022). "Thus, in canine melanoma, EGFR might be associated with other functions, such as cell differentiation and autophagy." (PMID 31996230, 2020). "The very low expression levels of EGFR in the H3 derived EVs could be in line with what has been described in other studies where the presence of EGFR appears to only be associated with a subset of melanomas." (PMID 32886718, 2020). "Another flavonoid compound, Herbacetin, from flaxseed and other sources exhibited promising anti‐angiogenic effects in human malignant melanoma by blocking EGFR‐ERK/AKT‐MMP9 signalling pathway." (PMID 41546170, 2026). "A375 cells are widely used NK–sensitive melanoma models and express EGFR, providing a system relevant to AREG biology." (PMID 41082397, 2026). "Targeting JAK1 and EGFR signaling successfully overcame BRAFi resistance in melanomas with low RNF125 expression, both in vitro and in in vivo xenograft models." (PMID 40872623, 2025). "These DMGs were involved in pathways related to pigmentogenesis, such as “Melanoma”, “EGFR tyrosine kinase inhibitor resistance”, and “Wnt signaling pathway”." (PMID 39857428, 2025).
melanoma (continued). "By blocking the ADAM17/EGFR/AKT/GSK3β pathway, RA prevents invasive proliferation and migration of human melanoma A375 cells, induces apoptosis, and increases the susceptibility of melanoma cells to cisplatin." (PMID 40427522, 2025). "In particular, a study showed that the downregulation of SOX10 in melanoma activated TGFβ to induce upregulation of EGFR and PDGFRβ, which then conferred resistance to MAPK inhibition." (PMID 40872623, 2025). "The anti-melanoma activity is enhanced by stimulation of the Epidermal Growth Factor Receptor (EGFR) during Th9 differentiation." (PMID 41030439, 2025). "Previous studies have shown that HBT can inhibit angiogenesis in malignant melanoma by blocking the EGFR-ERK/AKT signaling pathway." (PMID 41011177, 2025). "The RTK hyperactivation in melanoma is mainly due to EGFR, PDGFRβ, and IGF1R receptor overexpression or genetic mutations constantly activating RTK." (PMID 40872623, 2025). "The observed association with progressive disease (PD) and stable disease (SD) in our cohort suggests the existence of EGFR-driven melanoma subtypes, warranting further investigation into the functional consequences of EGFR activation." (PMID 40652269, 2025). "In melanoma and fibrosarcoma, overexpression of EGFR and ERBB2 sensitizes tumors to ferroptosis-inducing treatments through activation of the RAS/RAF/c-Myc/ACSL4 signaling axis." (PMID 40846695, 2025). "Ellagic acid decreases melanoma cells proliferation, viability, migration and invasion through modulation of the epidermal growth factor receptor pathway and suppression of the NF-κβ pathway." (PMID 40364408, 2025). "Oxidative stress regulator NRF2 has been shown to bind to the ARE element of EGFR in melanoma cells." (PMID 39843435, 2025). "Together, these results suggest that PTRF contributes to therapy resistance through upregulating EGFR in melanoma cells." (PMID 40745979, 2025). "EGFR expression in melanoma ranges from 0.8 to 1.75, which falls within the expected range of EGFR expression in melanoma tumor cells." (PMID 40869231, 2025). "The role of EGFR in melanoma progression has been confirmed using Xmrk, a mutant EGFR derived from Xiphophorus fish, which induces malignant melanoma in medaka fish." (PMID 38534309, 2024). "Melanoma is usually considered as a “hot” tumour, but some specific gene mutations such as COL3A1, EGFR, etc. can lead to decreased immune infiltration or increased immune checkpoints in TME." (PMID 39530091, 2024). "There are single-gene tests, like the ones that check for EGFR mutations in non-small cell lung cancer, or BRAF mutations in melanoma." (PMID 39199313, 2024). "We observed features of cellular senescence in NCSLC cells following EGFR inhibition and melanoma cells following BRAF inhibition." (PMID 38473364, 2024). "In any case, these findings point to AREG as a potential therapeutic target in CD133/EGFR-driven melanoma stem cells." (PMID 38727313, 2024). "EGFR (epidermal growth factor receptor) expression in melanomas has been found to impact metastasis to regional lymph nodes, thus indicating its association with tumor aggressiveness." (PMID 38534309, 2024). "Both melanocytes and melanoma have high EGFR phosphorylation activity, which makes it a promising target for EGFR inhibitors such Dacomitinib." (PMID 39627834, 2024). "In vitro experiments demonstrated that the resistance of melanoma cells was reduced by clearing senescent cells: EGFR–SRC–STAT3 pathway activation was upregulated in BRAFi‐resistant melanoma cells." (PMID 39161800, 2024). "The search terms “melanoma”, “mutation”, “surgery”, and “metastatic melanoma” and specific gene names (TMB, BRAF, NRAS, EGFR, c-KIT, MITF, etc.)were used in combination with the Boolean operators AND or OR." (PMID 38534309, 2024). "EGFR mutations activate signaling pathways associated with resistance to BRAF inhibitors and melanoma progression." (PMID 38534309, 2024).
melanoma (continued). "We also tested EGFR exon 19 (Del19 EGFR) deletions and KRAS Q61 mutations, and neither of these deregulations were found in the healthy skin, benign nevi, or melanoma samples." (PMID 38396984, 2024). "Previous reports have linked melanoma tolerance to BRAFi with RTK activity (e.g., AXL, FGFR, NGFR, and EGFR) and ERK reactivation." (PMID 39001489, 2024). "Despite melanoma being among the first tumors in which EGFR is suggested to be a metastatic marker, little is known about ErbB receptors in this cancer, and the literature about this issue is sometimes controversial." (PMID 38791617, 2024). "The current landscape of melanoma research, with its exploration of NRAS, TMB, BRAF, EGFR, c-KIT, and other mutations, offers a promising trajectory for future endeavors in understanding and combatting this disease." (PMID 38534309, 2024). "In silico mutational modeling and docking results have been applied as a tool to predict potential utility in predicting drug responses in EGFR-mutant NSCLC,28,29BRAF-mutant NSCLC,30BRAF-mutant melanoma, and ALK-mutated NSCLC." (PMID 39500140, 2024). "The EGFR-SFK-STAT3 signaling cascade plays a crucial role in the development of resistance to BRAF inhibitors in melanoma cells." (PMID 38534309, 2024). "While the importance of an AREG/EGFR loop in melanoma is less studied, a role for AREG expression in melanomagenesis has been demonstrated." (PMID 38727313, 2024). "Potential mechanisms highlighting the role(s) of CD133 and AREG in melanoma CSC were further delineated using AREG/EGFR inhibitors or siRNA knockdown of AREG mRNA." (PMID 38727313, 2024). "Increased expression of EGFR accompanied by reduced expression of HER3 was characteristic of the invasive subtype of BRAFi-resistant melanoma cells." (PMID 39175042, 2024). "Studies have demonstrated that the overexpression of EGFR in melanoma cells promotes their motility and proteolytic activity, ultimately modulating tumor invasiveness." (PMID 38534309, 2024). "The gene copy amplification of EGFR has also been correlated with melanoma progression and metastasis, with a prevalence of 55% in thicker cancers." (PMID 38534309, 2024). "Studies in murine melanoma models showed that activation of the EGFR pathway can lead to suppression of the immune responses by stimulating Tregs." (PMID 39148899, 2024). "A study by Girotti and others demonstrated that BRAFi-resistant melanoma cell lines express high levels of phosphorylated EGFR, and secrete increased levels of EGF." (PMID 37181747, 2023). "DCBLD2 has been suggested to trigger oncogenic processes in melanoma through Epidermal Growth Factor Receptor (EGFR) signaling." (PMID 36894939, 2023). "It has been reported that KIF22 can activate Epidermal Growth Factor Receptor (EGFR) signaling, an effective target for melanoma." (PMID 37944197, 2023). "Increased AR expression is sufficient to render melanoma cells BRAFi-resistant, eliciting transcriptional changes of BRAFi-resistant subpopulations, including elevated EGFR and SERPINE1 expression, of likely clinical significance." (PMID 37838724, 2023). "These have been stimulated kinases, like epidermal growth factor receptor (EGFR) in melanoma, B-Raf proto-oncogene, serine/threonine kinase (BRAF) in pulmonary cancer, and fms-like tyrosine kinase 3 (FLT3) in acute myeloid leukemia (AML) cases." (PMID 37062547, 2023). "Previous studies have shown that BBR decreased the phosphorylation of PI3K/AKT, ERK, and GSK3β in B16F10 melanoma cells and inhibited the activation of EGFR in these tumors." (PMID 37170144, 2023). "Using this strategy, we were able to detect palmitoylated phospho-EGFR in multiple tissue types and palmitoylated Ras in human melanoma samples." (PMID 36895631, 2023). "In the study of melanoma, several reports have demonstrated that the activation of EGFR/STAT3 signaling promotes the malignant progression of melanoma." (PMID 37944197, 2023).
melanoma (continued). "Activation of signal transducer and activator of transcription 3 (STAT3) signaling pathway: The EGFR-SRC family kinase (SFK)-STAT3 pathway is involved in vemurafenib resistance of melanoma." (PMID 37834284, 2023). "Collectively, KIF22 knockdown suppressed the proliferation and glycolysis and facilitated the apoptosis of melanoma cells by inactivating EGFR/STAT3 signaling." (PMID 37944197, 2023). "As the authors reported, incubation of WM115 and A375 melanoma cells with EA led to a reduction in EGFR expression." (PMID 37687080, 2023). "For instance, epidermal growth factor receptor (EGFR) T790M, KRAS G12A, and BRAF V600E mutations were found in the CSF-derived cfDNA of patients with metastatic lung cancer and melanoma who had initially responded to kinase inhibitors." (PMID 37958372, 2023). "Subsequently, melanoma cells were treated with EGF or Colivelin to further elucidate the regulatory effect of KIF22 on EGFR/STAT3 signaling." (PMID 37944197, 2023). "In another study, RA showed an inhibitory effect on melanoma cells via suppression of the ADAM17/EGFR/AKT/GSK3β axis resulting in the inhibition of melanoma cell proliferation, invasion, and migration." (PMID 37687080, 2023). "In contrast to its hyperactivation or overexpression, Ack1 is downregulated in vemurafenib-resistant melanoma with activated EGFR." (PMID 36980241, 2023). "In conjunction with overexpression of EGFR, metastatic melanoma cells are demonstrated to overproduce the epidermal growth factor (EGF) ligand." (PMID 37181747, 2023). "•KIF22 depletion suppresses proliferation, glycolysis and facilitates apoptosis of melanoma cells by inactivating EGFR/STAT3 signaling." (PMID 37944197, 2023). "Treatment with rosmarinic acid significantly reduced cell viability, proliferation, migrative and invasive abilities, and chemotherapy sensitivity of melanoma cells through inhibition of the ADAM17/EGFR/AKT/GSK3β axis." (PMID 36829966, 2023). "The cross-suppression of both AREG and EREG has also been reported to lead to the emergence of CTX resistance, which is related to the loss of cell addiction to EGFR, compensated by the hyperactivation and addiction to FGFR3 in melanoma." (PMID 36899869, 2023). "We demonstrated that GD2 and integrins form molecular complexes in lipid rafts and cooperate to enhance the malignant properties of melanomas by increasing the phosphorylation of EGFR and FAK41." (PMID 36973292, 2023). "Although the role of EGFR has been established in a range of neoplasms, in melanoma the results are conflicting." (PMID 37047539, 2023). "Taken together, the present study is the first to demonstrate that KIF22 knockdown suppresses the proliferation and glycolysis and facilitates the apoptosis of melanoma cells by inactivating EGFR/STAT3 signaling." (PMID 37944197, 2023). "Our model also postulates that the involvement of matrix metalloproteinases and EGFR signaling can contribute to the development of BRAF/MEK inhibitor resistance in melanomas." (PMID 37176114, 2023). "EGFR protein expression is a marker of melanoma metastasis, and a prognostic factor for survival outcomes." (PMID 37241912, 2023). "While other melanoma cell lines express variable levels of EGFR, the EGFR protein in both WM983A and WM983B cells is almost not detectable compared to other cell lines." (PMID 37333807, 2023). "By intersecting the key cluster and the intersection of drug-related genes and melanoma-related genes, we finally identified three crucial targets, EGFR, ERBB2, and CDK2, which are all protein serine/threonine kinases and are involved in cell cycle regulation." (PMID 38348352, 2023). "In vivo Nrf2 silencing has been shown the low EGFR expression and proliferation rate, preventing melanoma growth, and increasing tumor-free survival." (PMID 36747120, 2023). "It was reported that PRDX6 expression in melanoma cells is maintained in a post-transcriptional manner by EGFR-dependent signaling, implying a link between PRDX6 and EGFR signaling." (PMID 37529008, 2023).
melanoma (continued). "While investigating the effects of reduced pH on the survival and metastasis of human melanoma cells, Peppicelli and others identified that cells possessing an anoikis resistant phenotype expressed high levels of EGFR, and reduced levels of cleaved PARP-1." (PMID 37181747, 2023). "The EGFR mutant T790M/L858R showed significantly higher basal autophosphorylation in melanoma cell lines WM983A and WM983B." (PMID 37333807, 2023). "To assess the clinical significance of the results, we analyzed the transcriptomic profiles of melanoma cohorts, finding a strong positive correlation between expression levels of the AR and EGFR genes in multiple data sets." (PMID 37838724, 2023). "Summing up, KIF22 depletion represses proliferation, inhibits glycolysis, and accelerates apoptosis of melanoma cells by inactivating EGFR/STAT3 signaling." (PMID 37944197, 2023). "We expect, similar to findings in BRAFV600E mutated melanoma, that combining MEK and EGFR inhibition should also postpone SR and prolong survival of CRC patients." (PMID 37604687, 2023). "The findings from their study demonstrated that EA notably suppressed the proliferation, migration, and invasion of WM115 and A375 melanoma cells, and these effects were achieved by targeting the EGFR signaling pathway." (PMID 37687080, 2023). "In this article, we described a second‐generation MAPK Adaptive Resistance Model (MARM2.0) that seeks to explain the rewiring of EGFR/MAPK signaling occurring in drug adapted BRAFV600E melanoma cells." (PMID 36700386, 2023). "EGFR expression is repressed by gene methylation in melanomas, which confers sensitivity to BRAF inhibitors alone." (PMID 37422534, 2023). "In particular, autophosphorylation of EGFR with phosphorylation of the downstream pathways play prime roles in melanoma progression." (PMID 35208960, 2022). "Known for its ability to modulate tumor invasiveness, EGFR expression was demonstrated to correlate positively with poor survival and increased rates of metastasis in melanoma patients." (PMID 36432639, 2022). "Only 3 (6.4%) of the identified 47 CDx devices contained therapeutic class labeling, with two devices targeting EGFR mutations for the treatment of NSCLC and one targeting BRAF V600E and BRAF/MEK inhibitor combinations for melanoma." (PMID 35689144, 2022). "We have proven the human origin of EGFR in the developed M3-EGFR melanoma cell line by its ability to bind to human EGFR-specific monoclonal antibodies by flow-cytometry." (PMID 36432639, 2022). "Published attempts to develop an EGFR-expressing mouse melanoma model resulted in tumors, which, unfortunately, lost their EGFR expression in vivo in immunocompetent animals." (PMID 36432639, 2022). "The development of epidermal growth factor receptor (EGFR)-targeting agents for the treatment of malignant melanoma requires cheap and easy animal tumor models for high-throughput in vivo screening." (PMID 36432639, 2022). "EGFR overexpression is rather frequent in melanoma, mainly in its most deadly nodular and uveal subtypes." (PMID 36432639, 2022). "Sh-EGFl-1 has the ability to sustain a prolonged EGFR effect in melanoma cells because the cells are able to maintain their adherent properties, as well as survive and proliferate, albeit rather slowly." (PMID 36286420, 2022). "The viability of melanoma cells receiving EGFR inhibitor was reduced, suggesting that EGFR is a promising target for anticancer therapy." (PMID 35610275, 2022). "Jessen and collaborators reported that the knockdown of NRF2 in melanoma cell lines led to decreased proliferation and EGFR expression." (PMID 35326683, 2022). "CCT196969 seems to be an effective inhibitor of cell viability in EGFR-mutated melanoma, as well as in BRAF inhibitor resistant melanoma which has achieved resistance with upregulation of the STAT3 pathway." (PMID 36084109, 2022).